CDK6 (cyclin dependent kinase 6)
Diseases named in the same sentence as CDK6 in open-access papers (continued):
Sharing a sentence is not in itself a finding about the gene and the disease.
bladder cancer (continued). "APBB2 plays a dual regulatory role in bladder cancer, mediating the cell cycle through the CDK6 and MET pathways." (PMID 36532732, 2022). "Taken together, these results indicate that FTO targets CDK6 via the FTO/miR-576/CDK6 pathways in bladder cancer." (PMID 34725345, 2021). "We also demonstrated that FTO promoted bladder cancer cell proliferation via the FTO/miR-576/CDK6 pathways." (PMID 34725345, 2021). "Meanwhile, it is suggested that miR‐384 inhibits the tumorigenesis of renal cancer through regulating cyclin‐dependent kinase 6,30 which supports our finding that miR‐384 suppresses bladder cancer cell viability." (PMID 33634966, 2021). "Studies have shown that CDK6 promotes cell proliferation in bladder cancer as it does in other tumour types." (PMID 34725345, 2021). "Overexpression of circTCF25 can down-regulate the activity of miR-103a-3p and miR-107, increase the expression of CDK6, and promote the proliferation and migration of bladder cancer cells." (PMID 32820798, 2021). "The present study demonstrated that FTO exhibited an oncogenic role in bladder cancer via regulating the expression of cyclin-dependent kinases (CDK6), which are closely related to the cell cycle." (PMID 34725345, 2021). "Some of these genes were closely related to the occurrence and development of bladder cancer: CDK6, IL-10, and RUNX1, of which CDK4/6 inhibitors are a promising treatment strategy for the treatment of bladder cancer." (PMID 32655621, 2020). "In bladder cancer, circTCF25 downregulates miR-103a-3p and miR-107 as well as upregulates cyclin-dependent kinases 6 (CDK6), suggesting that circTCF25 is a new biomarker (Zhong, Lv & Chen, 2016)." (PMID 30155370, 2018). "Alterations of CDK6 expression have been well documented in bladder cancer and colorectal cancer tissues, respectively." (PMID 29207676, 2017). "Higher expression of CDK6 has been consistently detected in human bladder carcinoma tissues with immunohistochemistry and Western blot." (PMID 27484176, 2016). "Compared to the adjacent tissues, we found that the circTCF25 and CDK6 were highly expressed in bladder carcinoma tissues, while, miR-103a-3p and miR-107 were lowly expressed in bladder cancer." (PMID 27484176, 2016). "In bladder cancer, lncRNA GAS5 associates with CDK6 and reduces both CDK6 mRNA and protein levels, resulting in the inhibition of cell proliferation." (PMID 25959498, 2015). "Cyclin-dependent kinase 6 (CDK6), which promotes G1 progression and G1/S transition of the cell cycle, is a GAS5-associated protein in bladder cancer cells." (PMID 26198250, 2015). "The data presented in our study also identified a novel role for cell cycle protein CDK6 in bladder cancer through the coordination of cell cycle, migration and invasion." (PMID 25178497, 2014). "In our present study, similar expression pattern of CDK6 was observed in the human bladder cancer cell lines, which suggested the oncogenic role of CDK6 in bladder cancer." (PMID 25178497, 2014). "We also observed that inhibition of miR-320c or restoration of CDK6 in miR-320c-over-expressed bladder cancer cells partly reversed the suppressive effects of miR-320c." (PMID 25178497, 2014). "By targeting CDK6, miR-320c can inhibit proliferation and impair cell mobility in bladder cancer cells." (PMID 25178497, 2014). "We further demonstrated that knockdown of GAS5 increases CDK6 mRNA and protein levels in bladder cancer cells." (PMID 24069260, 2013). "We therefore thought that the role of GAS5 in regulating bladder cancer cell proliferation is mediated by modulating CDK6 expression." (PMID 24069260, 2013). "Gain-of-function and loss-of-function studies confirmed that GAS5 regulates cell cycle and inhibits bladder cancer cell proliferation, partly by regulating CDK6 expression." (PMID 24069260, 2013). "Knockdown of GAS5 induces a significant decrease in G0/G1 phase and promotes bladder cancer cell proliferation, at least in part, by regulating CDK6 expression." (PMID 24069260, 2013).
bladder cancer (continued). "Knockdown of GAS5 significantly increases CDK6 mRNA and protein levels in bladder cancer cell lines, but downregulation of GAS5 don’t change CDK2 and CDK4 expression level (data not shown)." (PMID 24069260, 2013). "Moreover, IGF2BP3 promoted both the proliferation and cisplatin resistance of bladder cancer cells by binding to the 5'- UTR region of CDK6 mRNA and enhancing its stability in an m6A-dependent manner." (PMID 40083693, 2025). "We investigated whether IGF2BP3 regulated CDK6 expression by modulating the stability of CDK6 mRNA in bladder cancer cells." (PMID 40083693, 2025). "When we explored the sensitivity of chemotherapy, flow cytometry demonstrated that knockdown of CDK6 could significantly increase the apoptosis rate of bladder cancer cells reduced by IGF2BP3." (PMID 40083693, 2025). "Notably, CDK6 interference or treatment with the small molecule CDK6 inhibitor palbociclib effectively counteracted the pro-proliferative effect induced by IGF2BP3 while sensitizing bladder cancer cells to cisplatin." (PMID 40083693, 2025). "To validate this hypothesis, we quantified mRNA levels of both IGF2BP3 and CDK6 in 44 pairs of bladder cancer tissues and adjacent normal tissues." (PMID 40083693, 2025). "CCK-8 assay results also showed that knocking down CDK6 gene expression could significantly reduce the IC50 of cisplatin in bladder cancer cells that were elevated due to over-expression of IGF2BP3." (PMID 40083693, 2025). "Similarly, EDU assay demonstrated that knockdown of CDK6 gene expression reversed the IGF2BP3 induced increase in DNA replication capacity of bladder cancer cells." (PMID 40083693, 2025). "Finally, a comprehensive characterization of CDK6 was applied in the prognostic prediction of bladder cancer, suggesting that targeting CDK6 represents a potential therapeutic option." (PMID 39310261, 2024). "Given the differences in assay platform, time, location, and dosage between the four experiments, it is encouraging to find shared genes that are relevant biologically; EGFR, CDK6, and CDC20 play key functions in cell cycle progression and have been implicated in bladder cancer." (PMID 37415126, 2023). "For example, miR-320c targets CDK6 to inhibit bladder cancer." (PMID 35902921, 2022). "Correlation of CDK6 expression and clinical-pathological features in Bladder carcinoma (BLCA)." (PMID 35463324, 2022). "Additionally, the expression of CDK6 decreased after miR-576 mimics transfection and increased after miR-576 inhibitor transfection into bladder cancer cells." (PMID 34725345, 2021). "Moreover, the expression of CDK6 increased significantly in FTO-overexpressing bladder cancer cells and decreased significantly in FTO knockdown bladder cancer cells." (PMID 34725345, 2021). "The expression of CDK6 increased significantly in bladder cancer tissues." (PMID 34725345, 2021). "Indeed, CDK6 has been found to be abnormally expressed in various types of malignant tumors such as bladder cancer and pancreatic cancer, and be a mediator in the regulation of them." (PMID 32310823, 2020). "In bladder cancer, circTCF25 acts as a miRNA sponge, suppressing the functions of miR-103a-3p and miR-107 in tumour tissues and increasing the expression of cyclin-dependent kinase 6 (CDK6), leading to tumour cell proliferation." (PMID 32758239, 2020). "Moreover, miR-320c is involved in the regulation of adipocytic differentiation of human mesenchymal skeletal stem cells and inhibits tumorous behaviors of bladder cancer by targeting CDK6." (PMID 26930277, 2016). "A previous study illustrated that CDK6 was over-expressed in bladder cancer tissue." (PMID 25178497, 2014). "Therefore, we further verified that miR-320c inhibited tumorous behaviors of bladder cancer cells by targeting CDK6." (PMID 25178497, 2014).
bladder cancer (continued). "Recently, it’s reported that miR-19a could act as an oncogenic microRNA in bladder cancer by targeting PTEN when miR-320c could inhibit tumorous behaviors of bladder cancer by targeting CDK6 and both of them could be potential biomarkers of bladder cancer." (PMID 25551284, 2014). "miR-320c could inhibit the proliferation, migration and invasion of bladder cancer cells via regulating CDK6." (PMID 25178497, 2014). "Thus, we confirmed that CDK6 was a key mediator of tumor suppression function of miR-320c in bladder cancer." (PMID 25178497, 2014). "Previous study indicated that the expression of CDK6 increased drastically in bladder cancerous tissues compared with their non-cancerous counterparts and elevated CDK6 expression resulted in the development of bladder cancer." (PMID 25178497, 2014). "Downregulated GAS5 promotes bladder cancer cell proliferation, partly by regulating CDK6, and thus may be helpful in the development of effective treatment strategies against bladder cancer." (PMID 24069260, 2013). "CDK6 is showed to be overexpressed in bladder cancer, and the concept has emerged that Rb phosphorylation by CDK4/6 leads not only to critical E2F-dependent transcription of essential cell cycle enzymes and regulators but also to assembly of the pre-replication complex in G1 phase." (PMID 24069260, 2013). "Furthermore, overexpression of GAS5 remarkably inhibits CDK6 expression in bladder cancer cell lines." (PMID 24069260, 2013). "In conclusion, our study demonstrated that IGF2BP3 regulated the cell cycle and cisplatin sensitivity in bladder cancer by enhancing CDK6 mRNA stability in an m6A-dependent manner, which maybe providing a new treatment strategy for bladder cancer patients, especially those with cisplatin resistance." (PMID 40083693, 2025). "Notably, CDK6 exhibited significant upregulation in bladder cancer tissues." (PMID 40083693, 2025). "Moreover, miR-576 represses CDK6 expression to promote bladder cancer cell proliferation." (PMID 36755807, 2023). "In addition, in our cell cycle analysis, the cell cycle was arrested in the G0/G1 stage after FTO knockdown, which might be explained by the corresponding decreased expression of CDK6 in bladder cancer cells." (PMID 34725345, 2021). "MiR-29c could inhibit the expression of CDK6 in bladder cancer." (PMID 34659534, 2021). "Considering that few studies have focused on how FTO promotes tumour formation by regulating miRNA synthesis, our study demonstrated that FTO could promote bladder cancer proliferation via the FTO/miR-576/CDK6 pathway by regulating the maturation of primiR-576 in an m6A-dependent manner." (PMID 34725345, 2021). "In addition, CDK6 was proven to be involved in the regulatory pathways in bladder cancer." (PMID 31212967, 2019). "In addition, in bladder carcinoma, it has been demonstrated that over-expression of circTCF25 could sponge miR-103a-3p and miR-107, increase CDK6 expression, and promote proliferation and migration in vitro and in vivo." (PMID 30692912, 2018). "Therefore, we supposed that circTCF25 could play a positive regulatory role on CDK6 to stimulate cell proliferation in bladder cancer." (PMID 27484176, 2016). "Moreover, we demonstrated miR-320c could induce bladder cancer cell cycle arrest and mobility via regulating CDK6." (PMID 25178497, 2014). "Therefore, downregulation of GAS5 increases CDK6 expression in bladder cancer cells." (PMID 24069260, 2013). "Together, we confirmed that CDK6 interference decreased the cell proliferation and cisplatin resistance induced by IGF2BP3 in bladder cancer cells." (PMID 40083693, 2025). "Then, we performed WB experiments on bladder cancer cell lines with knockdown or overexpression of IGF2BP3 to investigate the expression changes of multiple cyclin proteins CDK2, CDK4, CDK6, and CCND1." (PMID 40083693, 2025).
bladder cancer (continued). "Another experiment also proved that miR-381-3p blocks the dual regulatory role of CCNA2 (Cyclin-A2) in modulating CDK6 and MET-mediated cell-cycle pathway and EMT progression in bladder cancer." (PMID 36856518, 2023). "In bladder cancer tissues, the protein level of FTO was positively correlated with CDK6 and negatively related to miR-576." (PMID 35628623, 2022). "FTO promoted bladder cancer cell proliferation, migration and invasion via the FTO/miR-576/CDK6 pathways in an m6A-dependent manner." (PMID 34725345, 2021). "MiR-1180 is reported as a tumor suppressive miRNA in bladder cancer cells and inhibits cell proliferation and tumorigenicity by inhibiting cell cycle related proteins including CDK4, CDK6, cyclinD1, cyclinA2 expression and up-regulating p21 expression." (PMID 30936781, 2019). "It has been shown that miR-129-5p was deregulated in several tumor types including endometrial cancer, esophageal cancer, colon cancer and bladder cancer, and its verified target genes included SOX4, VCP/p97 and Cdk6." (PMID 24358111, 2013). "In bladder cancer, miR-381-3p has also been found to regulate the cell cycle of bladder cancer cells, increasing apoptosis rate by targeting negative regulation of CDK6, CCNA2, and MET." (PMID 38818039, 2024). "We discovered that bladder cancer patients with high CDK6 expression do not respond well to immunotherapy and have a poor prognosis." (PMID 39310261, 2024). "This is consistent with a study in bladder cancer, where knockdown of Cdk6 and SIRT-1 (direct targets of miR-34a) was not as effective reversing cisplatin resistance as miR-34a restoration." (PMID 35582270, 2019). "Ectopic over-expression of CDK6 (without the 3?-UTR) significantly abrogated the miR-320c-induced G1 arrest of bladder cancer cells and promoted cell proliferation and motility in vitro." (PMID 25178497, 2014). "In our study, an increased expression pattern of CDK6 was observed in the human bladder cancer cell lines UM-UC-3 and T24 compared with non-tumor urothelial cell line SV-HUC-1." (PMID 25178497, 2014). "Downregulated GAS5 increases bladder cancer cell proliferation, and a significant negative correlation is observed between the GAS5 and the CDK6." (PMID 24069260, 2013).
lung cancer (49 papers, 2013 to 2025). A malignant neoplasm involving the lung. "miR-137 inhibits the proliferation of lung cancer cells by targeting Cdc42 and Cdk6, while miR-145 can cause cell cycle arrest at the G0-G1 phase, decrease the S-phase, and inhibit proliferation." (PMID 37958720, 2023). "Previous studies have demonstrated that CDK6 promotes lung cancer cell proliferation by advancing the cell cycle, and that CDK6 expression is linked to overall survival in lung cancer patients." (PMID 40278596, 2025). "The experimental data indicated that YTHDF1, MAP3K6, and CDK6 were significantly over-expressed in lung cancer compared to adjacent normal tissues (p < 0.05)." (PMID 40278596, 2025). "Downregulation of CDK6 expression via miR-506 targeting induces G1 arrest; thus, hnRNP A2/B1 can eventually inhibit the proliferation of lung cancer cells." (PMID 38689093, 2024). "miR-137 in lung cancer cells significantly downregulates Cdc42 and Cdk6 and induces G1 cell cycle arrest, leading to a significant decrease in cell growth." (PMID 37958720, 2023). "Among the downstream targets of CRNDE, miR-641, CDK6, and miR-338-3p promote lung cancer cell proliferation and inhibit cell apoptosis." (PMID 36923797, 2023). "In clinical practice, lung cancer patients expressing a high level of CDK6 showed significant resistance towards CDK4/6i16." (PMID 37452037, 2023). "A previous study has revealed that miR-204 suppresses nonsmall cell lung cancer (NSCLC) progression through downregulating the CDK6 level." (PMID 36755807, 2023). "Here, we demonstrate that Leucine Rich Pentatricopeptide Repeat Containing (LRPPRC) controls CDK4/6i response in lung cancer by forming a feedback loop with CDK6." (PMID 37452037, 2023). "Their functional studies have confirmed competitive binding of MEG8 and CDK6 with miR-107 and their function in regulation of progression of lung cancer." (PMID 36114498, 2022). "In another genomic study of BM of various origin, several potentially actionable genomic alterations were associated with lung cancer BM, including AKT1, AURKA, CDK6, EGFR, MEK1, MET, and PIK3CA gene amplifications and CDKN2A deletions." (PMID 36561283, 2022). "In lung cancer H1299 cells, transfection of miR-449a/b has resulted in oncogenic CDK6 and CDC25A to be suppressed, leading to the dephosphorylation of pRB and decreased amount of E2F1 expression." (PMID 36303933, 2022). "Our findings reveal that miR-34a negatively regulates CDK6 expression and suppresses the malignant biological behaviors of lung cancer cells, which were consistent with the previous findings." (PMID 33796457, 2021). "Cyclin-dependent kinase 6 (CDK6) plays key roles in lung cancer cell proliferation and apoptosis, as well as being a candidate prognostic biomarker for non-small cell lung cancer." (PMID 33796457, 2021). "All data together indicated that the downregulation of c-Myc, HK2, PKM2, LDHA, PHGDH, PSAT1, cyclin D1, and CDK6 in lung cancer cells was related to the ubiquitin-protein degradation pathway, which was the result that the USP28 was inhibited by SGH." (PMID 33572615, 2021). "For instance, miR-137 is reported to inhibit the proliferation of lung cancer cells by targeting Cdc42 and Cdk6." (PMID 32433716, 2020). "Our results were consistent with a recent study indicating CDK6 as a direct target of miR-29b in lung cancer." (PMID 33177241, 2020). "We also found that CDK6 mRNA and protein levels were higher in lung cancer tissues than in normal tissues." (PMID 32767514, 2020). "Expression of cell cycle regulatory proteins CDK4, CDK6, and cyclin D1 was significantly decreased in ApoE knockdown lung cancer cells." (PMID 31275318, 2019). "Collectively, these data provide evidence that TRIM59 is involved in lung carcinoma growth and progression possibly through the induction of CDK6 expression and EMT process by activation of ERK pathway." (PMID 30515965, 2019).